CSPG4 (chondroitin sulfate proteoglycan 4)
Diseases named in the same sentence as CSPG4 in open-access papers (continued):
Sharing a sentence is not in itself a finding about the gene and the disease.
cancer (continued). "We cocultured CSPG4-targeting CAR-Ms with cancer cells for 48 h, FACS-isolated these CAR-Ms (“primed”), and evaluated infiltrative ability and phagocytosis capacity compared to CAR-Ms that had not interacted with cancer cells (“non-primed”)." (PMID 40082557, 2025). "CSPG4 is a ~ 300 kDa transmembrane proteoglycan that regulates cancer cell migration, invasion, epithelial-mesenchymal transition, and proliferation." (PMID 40082557, 2025). "We observed that the percentage of cancer cell killing was lower when CSPG4 CAR T cells were cocultured with the SW1736 and BCPAP cell lines, as compared to the 8505c and 2C-HCC cell lines." (PMID 40847369, 2025). "Chondroitin sulfate proteoglycan 4 (CSPG4) is involved in the progression of many cancers, such as undifferentiated thyroid cancer, squamous cell carcinoma of the head and neck, and basal breast cancer." (PMID 38877481, 2024). "Another strategy for the development of anti-cancer vaccines is using mimotopes, peptides that mimic an epitope on CSPG4, to induce a polyclonal antibody response against this antigen." (PMID 39409881, 2024). "In our study, a robust anoikis-related model was developed based on the expression levels of three genes: EHBP1, CSPG4, and PLOD1.The presence of these three genes has been linked to a variety of malignant tumors." (PMID 39664392, 2024). "It is well known that CSPG4 plays an important role in cell adhesion, motility, and invasion in various types of malignant tumors." (PMID 38338902, 2024). "The CSPG4 gene had been described as a potential target for cancer immunotherapy, and it was known to influence various immune cell subsets, indicating a potential role in immunotherapy efficacy." (PMID 39664392, 2024). "The signaling pathways and networks regulating expression of chondroitin sulfate proteoglycan 4 (CSPG4), a cancer-related protein that serves as a receptor for Clostridiodes difficile TcdB, are poorly defined." (PMID 36972308, 2023). "Though CSPG4 is important in both cancer and infection, little is known about the signaling networks regulating its expression." (PMID 36972308, 2023). "Using a biomarker discovery set consisting of 302 healthy controls and 165 malignant tumor patients, we found that the plasma ofCS-CD44, -SDC1, -CSPG4, and total ofCS in all types of cancer tested were significantly higher than that in healthy controls." (PMID 36746966, 2023). "We therefore tested CSPG4 surface expression in a panel of cancer cell lines derived from these entities (n=37)." (PMID 37849763, 2023). "Three ofCS modified glycoproteins (ofCS-CD44, SDC1, and CSPG4) detected across multiple cancer cells by rVAR2 were selected because of their important roles in cancer progression and metastasis." (PMID 36746966, 2023). "In line with this, CSPG4 was described to promote multiple steps of cancer development such as angiogenesis, dissemination, metastasis, proliferation, and survival." (PMID 37901209, 2023). "The CSPG4 contributes to malignancy and disease progression by promoting cancer cell adhesion, motility, and survival." (PMID 36768830, 2023). "To quantitate the plasma ofCS/ofCSPGs, we optimized an ELISA using different capture/detection pairs (rVAR2/anti-CD44, -SDC1, and -CSPG4) in a case-control study with six cancer types." (PMID 36746966, 2023). "Collectively, 11C/73- and 2C/165-expressing T cells specifically and efficiently recognized CSPG4+HLA-C*07:01+ cancer cells which warrants further preclinical and clinical evaluation of these TCRs." (PMID 37849763, 2023). "Our preliminary analysis of more than 350 cancer cell lines revealed a strong correlation between mRNA and protein expression levels, allowing us to base our study on CSPG4 mRNA expression." (PMID 35267618, 2022). "It has been reported that a major advantage of CSPG4-CAR-T cell therapy is its ability to target both primary TNBC cells and cancer-associated fibroblasts (CAFs) because CSPG4 is highly expressed on stromal cells in the TNBC TME." (PMID 35795050, 2022).
cancer (continued). "Published research has also shown a functional similarity between the role of CSPG4 as a mediator of cell differentiation, motility and tissue turnover in development, and its role in mediating key aspects of malignancy in cancer." (PMID 36428658, 2022). "Chondroitin sulfate (CS) proteoglycan 4 (CSPG4) is a cell surface proteoglycan that is currently under investigation as a marker of cancer malignancy, and as a potential target of anticancer drug treatment." (PMID 36428658, 2022). "The strong correlation between mRNA and protein expression levels of CSPG4 that we evidenced in 343 cancer cell lines suggests that CSPG4 protein expression parallels observations made at the transcriptomic level." (PMID 36221119, 2022). "In many cancer cell lines, the expression level of CSPG4 is significantly higher, suggesting a potential new target for the antibody-based immunotherapy of cancers." (PMID 35324891, 2022). "Following analysis of TCGA data, transcripts for CSPG4 were found to be significantly higher in several cancers compared to normal tissues, most notably HNSCC, and glioblastoma." (PMID 36428658, 2022). "Of note, the CSPG4 mRNA expression was strongly correlated with protein expression in a series of 369 cancer cell lines." (PMID 35267618, 2022). "A review of the literature suggests a role for CSPG4 in regulating cancer by driving changes in gene expression towards a malignant pathology." (PMID 36428658, 2022). "During the last years, CSPG4 was described as a potential target of cellular immunotherapy in cancers." (PMID 36221119, 2022). "CSPG4 allows cancer cells to proliferate and invade through the matrix leading to metastasis via downstream signaling pathways involving integrin-related signal transduction." (PMID 36110930, 2022). "This is particularly important given that CSPG4 targeting has been suggested as an anti-cancer treatment, however, therapies have shown minimal efficacy in patients." (PMID 36428658, 2022). "Of the top ten genes by correlation in HNSCC, many were found to have functions that support the known role that CSPG4 plays in cancer pathogenesis, such as cell migration, tissue remodelling and angiogenesis." (PMID 36428658, 2022). "These experiments demonstrate that PD-L1xCSPG4 binds to both PD-L1 and CSPG4 and that the strength of the interaction between the BsAb and CSPG4+/PD-L1+ cancer cells is primarily dominated by binding to CSGA4." (PMID 34069573, 2021). "Later, other surface components (Glypican-1, PD-L1, and CSPG4) were explored as cancer cell ENV markers as well and promising results stimulated further exploration of tumor-derived ENVs as cancer markers." (PMID 34359806, 2021). "CSPG4 presence was also detected in TNBC cancer stem cells, which are regarded as a major source for relapse and resistance." (PMID 33442419, 2021). "GSEA detected that CSPG4 contributed to cancer-related pathways, immune system process, and drug metabolism, which further confirmed its value in drug-resistance and immunotherapy of BCa." (PMID 35127724, 2021). "Together these flow cytometry-based binding assays demonstrated that the PDL1xCSPG4 BsAb has enhanced selectivity for CSPG4+/PD-L1+ cancer cells driven by avidity binding." (PMID 34069573, 2021). "These binding activities were replicated in several representative cancer cells endogenously expressing both CSPG4 or PD-L1." (PMID 34069573, 2021). "The transmembrane chondroitin sulfate proteoglycan 4 (CSPG4) has been shown to positively regulate cancer cell proliferation in various cancer entities and is currently under investigation for CTC capture and identification, as described in detail later." (PMID 32984308, 2020). "Overall, the anti-CSPG4-(PDD) conjugate is expected to internalize inside cancer cells that express the target antigen CSPG4." (PMID 32331483, 2020). "Another key proteoglycan seems to be CSPG4, with important roles for the regulation of cancer cell growth and invasion." (PMID 32984308, 2020).
cancer (continued). "In both cell lines after 7 days of treatment with ADC, we measured <5% of cells compared to PBS controls, suggesting that anti-CSPG4-(PDD) inhibited cancer cell proliferation during this extended time." (PMID 32331483, 2020). "Chondroitin sulfate proteoglycan 4 (Cspg4) is a membrane spanning proteoglycan expressed in immature progenitor cells and cancer cells." (PMID 32240230, 2020). "To test PASTMUS strategy in mapping functional elements of proteins, we selected three genes (ANTXR1, CSPG4, and HBEGF) encoding bacterial toxin receptors and three genes (HPRT1, PLK1, and PSMB5) encoding cancer drug targets." (PMID 31842968, 2019). "In this review, we want to highlight the potential of chondroitin sulfate proteoglycan 4 (CSPG4) as a CAR-target antigen for a variety of different cancer entities." (PMID 31779130, 2019). "Those CSPG4-positive stromal cells drive the invasion and anchorage-independent growth of cancer cells by supplying the pro-inflammatory cytokine IL-8." (PMID 31779130, 2019). "Initial efforts to specifically attack CSPG4 on cancer cells have encompassed monoclonal antibodies and immunotoxins." (PMID 31195686, 2019). "We have shown here that it is feasible to co-transfect the same T cells with a TCR specific for gp100 and a CAR specific for CSPG4 using a combined DNA- and RNA-based receptor transfer to generate TETARs for the use in adoptive T cell therapy of cancer." (PMID 31137488, 2019). "The CSPG4 has a key role in regulating the proliferative, migratory, invasive and metastatizing ability of cancer cells and their chemoresistance, therefore simultaneously regulating several processes needed for cancer development and progression." (PMID 29534457, 2018). "High levels of CSPG4 are expressed on invasive, chemotherapy-resistant, differentiated malignant cells and CICs, while the expression on indolent cancer cells and normal tissues is low." (PMID 29561763, 2018). "With some encouraging findings against CSPG4-expressing tumors, the potential of anti-CSPG4 antibodies against cancer would benefit from further in-depth research using novel constructs including those engineered with human Fc regions." (PMID 29375561, 2017). "In this review, we summarize reported functions of CSPG4 in cancer and we examine the development of ongoing immunotherapy strategies, most notably monoclonal antibodies that target CSPG4." (PMID 29375561, 2017). "CSPG4 represents a highly useful marker of aggressive and motile cancers, thus offering an excellent opportunity to target cancers that are notoriously resistant to conventional therapies." (PMID 28657611, 2017). "In this respect, hCFPs, TRAIL fusion proteins and DR5-agonistic bispecific antibodies targeted at CSPG4 are highly promising candidates for the treatment of highly aggressive cancers with a high recurrence rate and poor prognosis." (PMID 28657611, 2017). "This body of findings solidly demonstrated, in different cancer cells and in various experimental settings, the efficacy of anti-CSPG4 mAb in impairing cancer cell proliferation, migration and invasion." (PMID 28668095, 2017). "Disparate reports therefore point to potential contributions of CSPG4 in cancer growth, vascularization, dissemination, and metastasis." (PMID 29375561, 2017). "We next investigated the target antigen recognition and binding properties of engineered antibody variants against different cancer cell lines expressing cell surface HER2 or CSPG4." (PMID 28959256, 2017). "Together, long-emerging studies point to CSPG4 as a promising target for cancer therapies, including immunotherapies with monoclonal antibodies." (PMID 29375561, 2017). "Chondroitin-sulfate proteoglycan 4 (CSPG4) is a transmembrane glycoprotein overexpressed on malignant cells in several cancer types with only limited expression on normal cells." (PMID 28657611, 2017).
cancer (continued). "Monoclonal αCSPG4 antibodies have been shown to inhibit cancer progression by blocking ligand access to the CSPG4 extracellular binding sites." (PMID 28657611, 2017). "More evidence is required to clarify the exact mechanism through which CSPG4 promotes angiogenesis in cancer." (PMID 29375561, 2017). "This feature furthers the value of CSPG4 expression in cancer as a prognostic marker, particularly pertaining to metastasis, treatment resistance and probability of relapse." (PMID 28657611, 2017). "Of particular interest is the fact that CSPG4 is also putatively expressed by cancer stem cells (CSCs)." (PMID 28657611, 2017). "Even though certain anti-CSPG4 antibody clones showed promise for therapeutic application in different cancer types and in a number of in vitro and in vivo models, most of published studies were performed using antibodies with mouse Fc regions." (PMID 29375561, 2017). "In contrast, normal HPDE cells and seven other cancer cell lines showed barely detectable mRNA copies of CSPG4 (a range of 2–7 copies/104 copies of CPB)." (PMID 24932730, 2014). "CSPG4 expression in cancer cell lines was assayed using flow cytometry (FACS) and reverse-transcription PCR (RT-PCR)." (PMID 25197555, 2014). "We are currently identifying key domains of NEDD9 that binds to CSPG4 to further understand the mechanisms of cancer progression and metastasis." (PMID 22984505, 2012). "Also referred to as NG2 or Chondroitin Sulfate Proteoglycan 4, CSPG4 is a cell surface protein with significant roles in various biological processes and diseases, including cancer." (PMID 40918470, 2025). "Furthermore, CSPG4-specific mAb has been shown to inhibit growth, adhesion, and migration of cancer cells in vitro, and significantly reduces the tumorigenic power of cancer cells and mitigates metastases and recurrence in vivo." (PMID 38808892, 2024). "The specific roles of CSPG4 in cancer immune responses remain largely unexplored, necessitating further research to determine whether CSPG4 interactions can enhance CSPG4-targeted immunotherapy or mitigate negative immunomodulatory effects." (PMID 39409881, 2024). "Potentially, soluble CSPG4 in patient circulation may sequester anti-CSPG4 therapeutic agents, thus restricting their ability to reach and target CSPG4-expressing cancer cells in tissues." (PMID 39409881, 2024). "Outgoing signaling patterns upregulated in LE-LE signaling, relative to TC-TC signaling, included Collagen, Laminin, Tenascin, FN1, MIF, APP, CD99, Notch, and CSPG4 pathways, reinforcing the role of these pathways in facilitating cancer invasion and metastasis." (PMID 37596273, 2023). "Simultaneously, CSPG4 serves as a promising therapeutic target for cancer." (PMID 38015710, 2023). "Collectively, daily addition of decitabine for 6 days converts more than half of treated SKOV-3 cells to CSPG4-positive cells, which may render those cancer cells potentially sensitive to CSPG4-directed therapies, such as CSPG4-specific CAR-T cells." (PMID 36291817, 2022). "Despite the loss of sialic acid residues, we showed that glyco-engineered IgE produced and purified via this pipeline retained recognition of immune cells expressing both cognate IgE Fc receptors, FcεRI and CD23, as well as of cancer cells expressing the target antigen, CSPG4." (PMID 36362241, 2022). "Nevertheless, at the protein level, the expression of CSPG4 was more confined to cancer cells." (PMID 36291817, 2022). "Tenascin is upregulated with CSPG4 in wound healing and development, and it has been proposed that dysregulated expression of both CSPG4 and tenascin is a key feature of many pathologies, including cancer." (PMID 36428658, 2022). "Using tissue specimens obtained from blood cancer patients undergoing hypomethylating therapy with decitabine, could be valuable to carry out CSPG4 expression studies at the RNA and protein levels." (PMID 36291817, 2022).
cancer (continued). "Chondroitin sulfate proteoglycan 4 (CSPG4) is a cancer antigen which may be more selective for cancer cells." (PMID 36211808, 2022). "CSPG4 is a cell surface proteoglycan that is highly expressed across various types of human cancers with restricted expression in healthy tissues, making it an attractive target for antibody-based cancer immunotherapy." (PMID 36110930, 2022). "The fact that these genes are co-regulated with CSPG4 may suggest that SCCs acquire a stem cell phenotype as part of the pathology of malignancy, which is closely aligned to that shown by non-cancer skin stem cells." (PMID 36428658, 2022). "Results from our study may provide a basis for developing new toxin-based therapeutics to selectively target those cancer cells that express CSPG4." (PMID 35324891, 2022). "Next, they tested the role of CSPG4 mAb in PD-1/PD-L1 blocking capacity of PDL1xCSPG4 BsAb by replacing the CHO.PD-L1/CD3 cells with a CSPG4+/PD-L1+ cancer cell line (the CD3 stimulation of T cells was achieved by pre-treating the cells with BIS1; an EpCAM-directed CD3-agonistic bsAb)." (PMID 34069573, 2021). "In addition, a flow cytometry-based competitive binding assay was used to assess the overall binding strength (avidity) of PD-L1xCSPG4 BsAb to CSPG4+/PD-L1+ cancer cells." (PMID 34069573, 2021). "CSPG4 has been linked to many aspects of the metastatic cascade, including proliferation, migration, as well as ECM-remodeling and is expressed across many cancer types." (PMID 32984308, 2020). "CSPG4 expression was detected in various human cancers, including the majority of human UMs." (PMID 33348918, 2020). "Besides, CSPG4 presence was also detected in TNBC cancer stem cells, which are regarded as a major source for relapse and resistance." (PMID 31779130, 2019). "At the protein level, however, CSPG4 exhibited a stricter restriction to cancer cells." (PMID 31779130, 2019). "Using nanostring digital RNA counting, investigators from the national cancer institute (NCI) could confirm the presence of CSPG4 mRNA in a plethora of normal tissues, but at far lower levels than in malignant tissues (ratio tumors: normal tissues: 6.6)." (PMID 31779130, 2019). "In this study, we tested the use of anti-CSPG4 antibodies for staining and detection of cancer cells after rVAR2 capture, which could potentially be of future interest in the monitoring of anti-CSPG4 CAR-T therapies." (PMID 31466397, 2019). "Altered NG2/CSPG4 expression and/or distribution may serve as a prognostic factor in various cancer types (19, –, 23)." (PMID 29196603, 2018). "Despite these developments, the exact involvement of CSPG4 in the etiology of cancer is widely unknown." (PMID 29375561, 2017). "Furthermore, CSPG4 is believed to contribute to cancer growth and progression through promotion of angiogenesis." (PMID 29375561, 2017). "Actually, CSPG4 fragments have been widely described; tryptic products have been detected in sera from healthy donors and cancer patients but their biological and clinical significance is still fairly unknown." (PMID 28668095, 2017). "Here we have described CSPG4, a trans-membrane protein involved in numerous pro-oncogenic signaling pathways, as a target for recombinant immunotherapeutics in aggressive, therapy-resistant cancers." (PMID 28657611, 2017). "On the other hand, ERK1/2 signaling blockade leads to reduced CSPG4-dependent cancer cell motility." (PMID 29375561, 2017). "Practically, such a central oncogenic role may represent a druggable Achilles’ heel for rational-designed CSPG4-targeted cancer therapy." (PMID 28657611, 2017). "Moreover, CSPG4-directed antibody conjugates have been shown to be selectively internalized by CSPG4-expressing cancer cells via endocytosis." (PMID 28657611, 2017). "The definitive roles for CSPG4 in the immunology of cancer are however still widely unexplored." (PMID 29375561, 2017).